PPP2R2C (protein phosphatase 2 regulatory subunit Bgamma)
Description:
The B regulatory subunit might modulate substrate selectivity and catalytic activity, and might also direct the localization of the catalytic enzyme to a particular subcellular compartment.
Synonyms: PR52; IMYPNO; MGC33570; PR55G; B55gamma; B55-GAMMA; IMYPNO1
Tractability: PROTAC: ubiquitination databases record sites on it; its protein half-life has been measured.
Gene: Protein-coding gene on chromosome 4 (6,320,578 to 6,563,600, reverse strand). Ensembl gene ENSG00000074211.
Subcellular location (Human Protein Atlas): Cytosol
Gene Ontology:
Molecular function: protein binding; protein phosphatase regulator activity
Cellular component: cytosol; protein phosphatase type 2A complex
Genetic constraint (gnomAD): Loss-of-function variants: 10 observed, 45.19 expected, observed/expected ratio (o/e) 0.22, 90% interval 0.14 to 0.38. The upper end of that interval is the gene's LOEUF score, 0.38, which puts it in group 1 of 6, group 1 being the genes least tolerant of losing a copy. Missense variants: 308 observed, 635.01 expected, observed/expected ratio (o/e) 0.49, 90% interval 0.44 to 0.53. Synonymous variants: 257 observed, 250.64 expected, observed/expected ratio (o/e) 1.03, 90% interval 0.93 to 1.14.
Homologues: Orthologues: pig PPP2R2C (99% identical), mouse Ppp2r2c (99% identical), chimpanzee PPP2R2C (96% identical), macaque PPP2R2C (96% identical), rat Ppp2r2c (95% identical), guinea pig PPP2R2C (94% identical), tropical clawed frog ppp2r2c (94% identical), rabbit PPP2R2C (83% identical), zebrafish ppp2r2ca (83% identical), zebrafish ppp2r2cb (76% identical), Caenorhabditis elegans sur-6 (63% identical). Paralogues in human: PPP2R2B (86% identical), PPP2R2D (81% identical), PPP2R2A (80% identical).
Diseases named in the same sentence as PPP2R2C in open-access papers:
PPP2R2C is named in the same sentence as 34 diseases in open-access papers, as found by Europe PMC text mining. Sharing a sentence is not in itself a finding about the gene and the disease. The quoted sentences say what the papers report.
glioma (4 papers, 2015 to 2025). A benign or malignant brain and spinal cord tumor that arises from glial cells (astrocytes, oligodendrocytes, ependymal cells). "Alongside, PPP2R2C, which encodes a gamma isoform of the subunit B55 subfamily, was also reported to be downregulated in various glioma cell lines and glioma patients." (PMID 31884567, 2020). "The restoration of PPP2R2C expression in glioma cells inhibited colony formation and suppressed cancer cell proliferation in both in vitro and in vivo models." (PMID 41146310, 2025). "miR-1301-3p acts as oncogene that accelerates the process of prostate carcinogenesis through targeting PPP2R2C and anti-oncogene by inhibiting cell proliferation in glioma." (PMID 33987098, 2021).
prostate carcinoma (4 papers, 2015 to 2025). A carcinoma that arises from epithelial cells of the prostate gland. "Currently, there is little direct evidence connecting specific PPP2R2C splice variants to treatment-resistant GBM or prostate cancer." (PMID 41146310, 2025). "In summary, we propose that GHSROS is an oncogene that regulates cancer hallmarks and the expression of a number of genes, including the tumor suppressor PPP2R2C – the loss of which is an emerging alternative driver of prostate cancer." (PMID 33585078, 2021). "Notably, GHSROS modulates the expression of PPP2R2C, the loss of which may drive androgen receptor pathway-independent prostate tumor progression in a subset of prostate cancers." (PMID 33585078, 2021). "Consistently, forced overexpression or knockdown of GHSROS in prostate cancer cell lines reciprocally regulated endogenous PPP2R2C expression." (PMID 33585078, 2021). "We provide evidence that this lncRNA reprograms prostate cancer cells toward a more aggressive phenotype, possibly by repressing the expression of the tumor suppressor PPP2R2C to allow androgen-independent growth." (PMID 33585078, 2021). "We demonstrate that PPP2R2C expression in prostate cancer cell lines is repressed by forced GHSROS overexpression and increased by GHSROS knockdown." (PMID 33585078, 2021). "Although seemingly paradoxical, GHSROS repression of AR and PPP2R2C in prostate cancer cell lines can be rationalized." (PMID 33585078, 2021). "Our study not only highlights genes modulated by GHSROS, but also genes (such as ZNF467, CHRDL1, and PPP2R2C) that may be generally relevant to prostate cancer progression." (PMID 33585078, 2021).
brain tumors (3 papers, 2015 to 2025). "For instance, in the glia cells of brain tumors, glioblastoma (GBM) downregulation or loss of the regulatory subunit PPP2R2C has been reported." (PMID 41146310, 2025). "In this context, PPP2R2C is of particular importance because of its almost exclusive occurrence in the brain and its contribution primarily to brain disorders (neurodegenerative diseases, learning disabilities, and brain tumors)." (PMID 41146310, 2025). "A subtype of medulloblastoma, pediatric brain tumors, are characterized by high expression of the chemokine receptor CXCR4 and concordant suppression of PPP2R2C." (PMID 33585078, 2021).
Insulin resistance (2 papers, 2022). Increased resistance towards insulin, that is, diminished effectiveness of insulin in reducing blood glucose levels. "Moreover, the Integrative Genomics Viewer (IGV) showed an enriched RARγ binding signal on the promoter regions of representative genes such as Socs3, Ptprf and Ppp2r2c, which are associated with the promotion of insulin resistance signaling." (PMID 36175396, 2022). "The first locus (index SNP: rs6446490, Pmeta = 2.30 × 10–13) was mapped on PPP2R2C, a gene that increased insulin resistance." (PMID 36187959, 2022).
nasopharyngeal carcinoma (2 papers, 2019 to 2026). A carcinoma arising from the nasopharyngeal epithelium. "miR-572 also can induce proliferation, invasion and inhibit apoptosis of nasopharyngeal carcinoma cells by targeting protein phosphatase 2 regulatory subunit Bgamma." (PMID 30863671, 2019).
amyotrophic lateral sclerosis (1 paper, 2014). Amyotrophic lateral sclerosis (ALS) is a neurodegenerative disease characterized by progressive muscular paralysis reflecting degeneration of motor neurons in the primary motor cortex, corticospinal tracts, brainstem and spinal cord. "In FTDC, PIF promotes bone morphogenetic protein pathway (SMAD1, 53-fold) and axonal guidance genes (EPH5) while inhibiting PPP2R2C, negative cell-growth regulator, involved in Alzheimer’s and amyotrophic lateral sclerosis." (PMID 26085845, 2014).
astrocytomas (1 paper, 2015). "Among the mRNAs with the raw gProcessed Signal > 500, two of the 5 most upregulated mRNAs (Tenascin-C, Aquaporin-1) and two of the 5 most downregulated mRNAs (HAPLN4, PPP2R2C) were validated in the training set (40 astrocytomas and 20 NAT samples)." (PMID 26252651, 2015). "Tenascin-C, and Aquaporin-1 were significantly upregulated in astrocytoma tissues compared with NAT samples, while HAPLN4 and PPP2R2C were significantly downregulated." (PMID 26252651, 2015).
bipolar disorder (1 paper, 2020). A disorder of the brain that causes unusual shifts in mood, energy, activity levels and the ability to carry out day-to-day tasks. "Interestingly, PR55/Bγ (encoded by the PPP2R2C gene) is a pivotal phosphatase in the brain, and single-nucleotide polymorphisms (SNPs) of PPP2R2C are involved in several mental disorders, including ADHD, bipolar disorder and schizophrenia." (PMID 32291379, 2020).
brain cancer (1 paper, 2021). A primary or metastatic malignant neoplasm affecting the brain. "PPP2R2C also has a classical growth-inhibiting tumor suppressor role in brain cancers." (PMID 33585078, 2021).
coronary artery disease (1 paper, 2023). "PPP2R2C has previously been associated with BMI, coronary artery disease, T2D, and metabolite levels." (PMID 37669986, 2023).
esophageal adenocarcinoma (1 paper, 2021). A malignant tumor with glandular differentiation arising predominantly from Barrett mucosa in the lower third of the esophagus. "Loss of PPP2R2C expression has been attributed to esophageal adenocarcinoma tumorigenesis, and PPP2R2C downregulation by distinct microRNAs positively correlates with increased proliferation of cultured cancer cells derived from the prostate, nasopharynx, and ovary." (PMID 33585078, 2021).
inflammatory bowel disease (1 paper, 2022). A spectrum of small and large bowel inflammatory diseases of unknown etiology. "Interestingly, as per GeneCards, the PPP2R2C gene was already reported to be involved in cell cycle regulation, beta-adrenergic receptor signaling, and PI3-Akt signaling, as well as being responsible for inflammatory bowel disease." (PMID 35571016, 2022).
lung adenocarcinoma (1 paper, 2021). A carcinoma that arises from the lung and is characterized by the presence of malignant glandular epithelial cells. "Forced overexpression of GHSROS in the A549 lung adenocarcinoma cell line decreased AR and PPP2R2C expression (Student’s t-test, P ≤ 0.0001)." (PMID 33585078, 2021).
melanoma (1 paper, 2013). A malignant, usually aggressive tumor composed of atypical, neoplastic melanocytes. "This leaves WNT4, CHP2, PPP2R2C and COL11A1 which have not been previously reported to be associated with melanoma." (PMID 23638386, 2013). "However, six signature genes (i.e., IL8, SHC4, COL11A1, CHP2, PPP2R2C and WNT4) were not reported previously by microarray-based melanoma studies, although two (i.e. IL8 and SHC4) have been identified in independent wet-lab studies." (PMID 23638386, 2013).
mental disorder (1 paper, 2020). A disease that has its basis in the disruption of mental process. "PR55/Bγ (encoded by the PPP2R2C gene) is a pivotal phosphatase in the brain, and single-nucleotide polymorphisms (SNPs) of PPP2R2C are involved in several mental disorders." (PMID 32291379, 2020).
narcolepsy (1 paper, 2020). A sleep disorder characterized by a tendency for excessive sleepiness during the day which occurs even after adequate sleep in the nighttime. "Located within the gene, the functions PPP2R2C, GPM6A, EPHX2, NKAIN3, ZNF365, TENM4, and PR2Y11 are related to narcolepsy." (PMID 32358372, 2020).
ovarian carcinoma (1 paper, 2022). A malignant neoplasm originating from the surface ovarian epithelium. "In ovarian cancer, there is upregulation of EIF4A3, whereas suppression of PPP2R2C leads to ovarian cancer cell proliferation." (PMID 35628146, 2022).
ovarian clear cell cancer (1 paper, 2021). An invasive malignant neoplasm that arises from the ovary and is characterized by a predominance of clear and hobnail malignant epithelial cells. "GHSROS knockdown in the ES-2 ovarian clear cell carcinoma cell line, which does not express PPP2R2C, increased the expression of AR (Student’s t-test, P = 0.0029 and P = 0.0022)." (PMID 33585078, 2021).
personality disorder (1 paper, 2022). A diverse category of psychiatric disorders characterized by behavior that deviates markedly from the expectations of the individual's culture; this pattern of deviation is pervasive and inflexible and is stable over time. "The GTP-binding RAS-like 2 gene (DIRAS2), which regulates neurogenesis, as well as protein phosphatase 2, regulatory subunit B, gamma (PPP2R2C) gene located in the 4P16 region, channel-interacting protein 4 (KCNIP4) and SPOCK gene, is also associated with adult ADHD and personality disorders." (PMID 36317794, 2022).
prostate tumor (1 paper, 2021). "Loss of PPP2R2C expression alone is thought to reprogram prostate tumors towards AR pathway-independent growth and survival." (PMID 33585078, 2021).
type 2 diabetes (1 paper, 2022). "In line with our research, a SNP variant of the PPP2R2C gene (rs4689388) at the alleles G/A has been associated to type 2 diabetes." (PMID 35013117, 2022). "The validation analysis showed two statistically significant CpGs with the rank regression method related to two genes associated to metabolic traits, PPP2R2C and CHST1, which have been linked to the metabolic trait type 2 diabetes." (PMID 35013117, 2022). "The genes PPP2R2C and CHST1 have both been linked to the metabolic traits type 2 diabetes through GWAS studies." (PMID 35013117, 2022).
cancer (9 papers, 2008 to 2025). A tumor composed of atypical neoplastic, often pleomorphic cells that invade other tissues. "Unfortunately, due to the elusive nature of PP2A’s mechanisms and the limited research on PPP2R2C splice variants, there is a significant gap in understanding their role in cancer resistance." (PMID 41146310, 2025). "While the PP2A complex (containing PPP2R2C) is known to influence cancer progression, major genomic studies, such as TCGA and CPTAC, have not systematically examined the gene’s alternative splicing patterns." (PMID 41146310, 2025). "Several independent lines of evidence suggest that PPP2R2C is a critical tumor suppressor involved in many cancers." (PMID 33585078, 2021). "However, the mechanisms of miRNAs on cancer cell activities through regulating the expression of PPP2R2C need to be further investigated." (PMID 34550272, 2021). "FBP1 was significantly associated with overall survival outcomes in 10 cancers while PPP2R2C and PPP2R2B in 8 cancers." (PMID 32807122, 2020). "Moreover, reduced PP2A activity due to PPP2R2C dysfunction hyperactivates survival pathways, such as PI3K/AKT and MAPK/ERK, further enabling cancer cells to evade apoptosis and enhance survival therapeutic stress." (PMID 41146310, 2025). "For immune-related genes, the expression of genes involved in the categories of tight junction such as MYH11, PPP2R2C, and MYL9, cancer development such as TAGLN and CALD1, and acquired immunity such as PCP4 and CXCL13 was upregulated in the LP group when compared with that in the CON group." (PMID 37731924, 2023).
tumor (9 papers, 2015 to 2025). "In recent years, the expression of PPP2R2C, which encodes for the B55γ protein, has gained increasing attention due to its unique, tissue-specific distribution and emerging role in tumor biology." (PMID 41146310, 2025). "InccRCC, a 4-gene model comprising KIF4A, UBE2C, OTX1, and PPP2R2C showed great potential to distinguish tumour tissues from normal ones." (PMID 41361459, 2025). "Accordingly, PPP2R2C has been proposed to act as a tumor suppressor in brain cancer and as a biomarker for tumor progression and prognosis." (PMID 41146310, 2025). "Nonetheless, the role of PPP2R2C in our results has been questioned, which showed a lower expression in the high-grade group, implying a tumor-suppressor role." (PMID 34550272, 2021). "Notably, enrichment of the PP2A regulatory subunit PPP2R2C, together with other phosphatases, has been observed in PyMT tumor-infiltrating CD8+ T-cells, suggesting a broader mechanism of phosphatase-mediated immunosuppression." (PMID 41146310, 2025). "In a subsample of patients whose tumours were profiled for RNA (n = 96), feature S(1,−1)SumAverg was significantly associated with the expression of gene MOV10L1, LRP1B, ZFY, PITX2, TRAPPC12, MMGT1 and PPP2R2C (all P < 0.05)." (PMID 36050449, 2022). "Precisely how GHSROS mediates PPP2R2C downregulation and its effects on tumor growth remains to be determined, however, GHSROS is the first lncRNA shown to downregulate this critical tumor suppressor, suggesting a role in adaptive survival pathways and CRPC development." (PMID 33585078, 2021). "Several of those genes are known tumor suppressors that are hypermethylated in solid cancers (CACNA1G, IRF6, ITGA9, and PPP2R2C) and used as biomarkers related to adverse outcome." (PMID 30285865, 2018). "The selective transcriptional downregulation of ubiquitin ligase adaptors and PP2A phosphatase regulatory isoforms PPP2R2C and PPP2R2D in GBM versus AS, ODG, and non-tumor brain samples suggested an intricate role of the ubiquitination machinery on Hippo signaling." (PMID 35896929, 2023). "Our experimental result confirmed the slightly higher level of PPP2R2C in high-grade HNC, implying it may serve as a tumor-promoting gene, but without significant statistical difference (P>0.05)." (PMID 34550272, 2021).
neurological disorders (1 paper, 2024). "Intriguingly, both PPP2R2B and PPP2R2C have been associated to neurological disorders." (PMID 38331954, 2024).
PPP2R2C also shares sentences with these, for which no sentence is quoted: Intellectual disability (2 papers); clear cell renal cell carcinoma (1); glioblastoma (1); medulloblastoma (1); memory impairment (1); Obesity (1); rectal cancer (1); rectum tumors (1); schizophrenia (1); tauopathies (1).